CIMIP3 (ciliary microtubule inner protein 3)
Synonyms: GUCA1ANB
Tractability: No criterion of Open Targets' tractability assessment is met for any kind of drug.
Gene: Protein-coding gene on chromosome 6 (42,142,693 to 42,163,418, forward strand). Ensembl gene ENSG00000287363.
Subcellular location: Cytoplasm, cytoskeleton, flagellum axoneme
Homologues: Orthologues: chimpanzee CIMIP3 (96% identical), macaque CIMIP3 (89% identical), pig CIMIP3 (78% identical), dog CIMIP3 (75% identical), mouse Cimip3 (69% identical), guinea pig CIMIP3 (66% identical), rat Cimip3 (65% identical).